VDR (vitamin D receptor)
Diseases named in the same sentence as VDR in open-access papers (continued):
Sharing a sentence is not in itself a finding about the gene and the disease.
prostate carcinoma (continued). "Circulating vitamin D concentrations and the vitamin D receptor, of which both are partly genetically determined, may be associated with the risk of lethal prostate cancer but most probably not with the risk of prostate cancer incidence." (PMID 35229338, 2022). "In addition, the status of VDR expression may be determinant for the development of prostate cancer." (PMID 32560347, 2020). "However, recent findings demonstrated that isoforms of VDR, vitamin D-metabolizing genes and DBP may be associated with prostate cancer risks or clinical outcomes." (PMID 32560347, 2020). "Some in vitro studies using VDR-expressing prostate cancer LNCaP cells reported that EB108928, a potent analogue of 1,25D3 as well as 1,25D329 has inhibitory effects on the growth of cancer cells, implying that 1,25D3 might be effective as a therapeutic reagent for prostate cancer in some cases." (PMID 29899561, 2018). "Furthermore, as PCa is hormonally driven, the crosstalk between AR and VDR in prostate cancer was previously investigated, reporting that AR activation inhibits VDR-mediated transcription through the activity of different coregulatory proteins such as prohibitin, ARA70, or ZNF366." (PMID 28811844, 2017). "Evidence failed to support the role of VDR Cdx2 and ApaI polymorphisms in prostate cancer." (PMID 27553621, 2016). "However, VDR SNPs have not been consistently associated with 25(OH)D or 1,25(OH)2D concentrations or with prostate cancer risk." (PMID 25488826, 2015). "Vitamin-D receptor (VDR): The vitamin D3 receptor (VDR) is an intracellular hormone receptor that specifically binds the active form of vitamin D (1, 25-dihydroxyvitamin D3 or calcitriol), which has been shown to promote differentiation and inhibit the proliferation of prostate cancer cells." (PMID 24282788, 2013). "However, the involvement of the AS3 gene product into androgen receptor signaling and vitamin D receptor action in prostate cancer cells suggests that inactivation of AS3 may contribute to the development of androgen-independent prostate cancer." (PMID 19737411, 2009). "The vitamin D receptor (VDR) plays a crucial role in regulating the growth and differentiation of prostate cancer cells." (PMID 40362574, 2025). "Our study identified that genomic ancestry drives the VDR complex composition, genomic distribution, and transcriptional function, and is disrupted by BAZ1A and illustrates a novel driver for AA prostate cancer." (PMID 37082578, 2023). "After a well‐known ERRα regulator, KDM1A, was recently observed to be involved in the corruption of vitamin D signaling in prostate cancer, we assessed the ERRα‐KDM1A connection in the VDR pathway of BC." (PMID 34003583, 2022). "Vitamin D Receptor (VDR) has been commonly found in different types of cancer cells including but not limited to breast and prostate cancer cells." (PMID 34737683, 2021). "The VDR is expressed in the DU145 and PC-3 prostate cancer cell lines and treatment with calcitriol inhibits proliferation and maintains differentiation of these cells." (PMID 33179012, 2020). "As shown in prostate cancer xenograft mice, LSD1 and VDR are present in the same transcriptional complex in the nucleus, mutually interacting to regulate cancer progression through epigenetic mechanisms." (PMID 32560347, 2020). "The current literature on the functions of NRs in prostate cancer indicate that DAX1, SHP, RARβ/γ, FXRs, LXRs, VDR, ERβ, ERRβ/γ, and MR can play antioncogenic roles, while PPARγ, RORγ, SF-1, LRH-1, Erα, and GR, as well as AR, can play oncogenic roles." (PMID 31212954, 2019). "Conversely, analysis of RANKL and VDR showed a putative correlation among the presence of RANKL and/or VDR positive prostate cancer cells, bone metastasis formation, and microcalcifications." (PMID 30627063, 2018). "One confounding factor is that many prostate cancers express a TMPRSS2:ERG fusion gene whose expression is increased both by androgens and by vitamin D receptor (VDR) activation." (PMID 28591703, 2017).
prostate carcinoma (continued). "No significant variations in VDR expression were observed based on the age or race/ethnic origin of patients with prostate cancer." (PMID 39963174, 2025). "The enrichment of motifs suggested the VDR cistromes were comparable in nonmalignant cells, and distinct from prostate cancer cells." (PMID 37082578, 2023). "Using prostate cancer cell lines in vitro, we have previously shown that S179D PRL sensitizes DU145 and PC-3 cells to the anti-tumor effects of physiological concentrations of calcitriol through its ability to increase expression of the VDR." (PMID 33179012, 2020). "In addition to effects via induction of the VDR, S179D PRL has additional anti-prostate cancer benefit derived from interruption of the autocrine PRL growth loop mediated through PRLRLF signaling." (PMID 33179012, 2020). "Also, linear regression analysis showed a significant correlation between 18F–choline uptake and the number of vimentin, RANKL, VDR, or PTX3 positive prostate cancer cells." (PMID 31614564, 2019). "In prostate cancer, treatment with the PRL inhibitor S179D PRL upregulated the expression of SF1b thus leading to upregulation of p21, a cell cycle inhibiting protein, and the vitamin D receptor known to promote differentiation." (PMID 21144038, 2010). "In prostate cancer cells, indeed, the direct interaction between VDR and specificity protein 1 (sp1) which, in turn, modulates p27 transcription, seems to be the common mechanism modulating expression of genes without VDR responsive elements." (PMID 32560347, 2020). "Similarly, there is lacking of comprehensive information of in vivo VDR-mediated pathways in prostate cancer tissues." (PMID 21991434, 2011). "In prostate cancer cells, these effects would be anticipated to counteract the anti-proliferative effects of 1,25(OH)2D3, suggesting that not all interactions between AR- and VDR-mediated signaling are beneficial." (PMID 21592394, 2011). "The vitamin D receptor (VDR) is expressed in non-epithelial prostate cancer cells and the benign stroma surrounding prostate tumors, suggesting that vitamin D may modulate the prostate tumor microenvironment, particularly in the context of antiandrogen therapy." (PMID 40362574, 2025). "Furthermore, the effects of VDR knockdown on tumor growth, cancer cell proliferation and apoptosis observed in vitro were fully reproducible in vivo, evident not only in bone but also in soft tissues, and independent of whether human breast or prostate cancer cell lines were used." (PMID 28944088, 2017). "Thus, a CYP24A1 resistant VDR agonist may be beneficial for treatment of TMPRSS2:ERG positive prostate cancer; one negative consequence of TMPRSS2:ERG expression is inactivation of VDR signaling." (PMID 28591703, 2017).
melanoma (101 papers, 2004 to 2025). A malignant, usually aggressive tumor composed of atypical, neoplastic melanocytes. "This research found an inverse correlation between melanin levels in uveal melanoma and VDR expression, suggesting vitamin D metabolism’s role in melanoma and offering potential diagnostic and therapeutic insights for uveal tract disorders." (PMID 40334012, 2025). "Single nucleotide polymorphisms (SNPs) in the VDR gene can affect the expression and/or function of the VDR protein, potentially influencing the incidence and natural history of melanoma." (PMID 38927967, 2024). "The FokI (C/T-rs2228570) and BsmI (rs1544410) mutations are among the several SNPs found in the VDR gene that have been widely used in melanoma research." (PMID 38672780, 2024). "The proliferation of both normal and pathological melanocytes, including melanoma cells, has been linked to modifications in the vitamin D endocrine system, which includes the VDR." (PMID 38672780, 2024). "The VDR polymorphism rs1544410 has been linked to an elevated risk of melanoma and an increased thickness of Breslow tumors." (PMID 38672780, 2024). "Studies have shown that VDR single nucleotide polymorphisms have been linked to poor survival rates in patients with melanoma." (PMID 38672780, 2024). "Another locus for which mutations are associated with increased probability of melanoma is VDR encoding the vitamin D receptor, a regulator of multiple phenotypic traits that will be discussed in the following subchapters." (PMID 38927967, 2024). "These were confirmed by in vitro inhibition of human melanoma growth associated with inhibition of Wnt signaling, and reduced ability to form lung metastases by B16 melanoma overexpressing VDR was again associated with decreased Wnt/β-catenin signaling." (PMID 38927967, 2024). "Vitamin D deficiency was associated with decreased survival in primary melanoma, especially when VDR levels were low." (PMID 37892558, 2023). "Vitamin D deficiency shortened survival in melanoma-bearing mice, while VDR overexpression mitigated metastasis." (PMID 37686465, 2023). "The aim of this study was to investigate the association of BsmI and ApaI VDR polymorphisms among patients with non-melanoma cancers and controls." (PMID 33255834, 2020). "Localization of VDR expression is also important as lower expression of cytoplasmic VDR was found more commonly in melanoma as compared to nevi and also associated with tumor size." (PMID 32429485, 2020). "Such an association has been recently confirmed by a meta-analysis, which reviewed 11 studies in European populations and analyzed the association between VDR FokI, BsmI, TaqI, ApaI, and EcoRV polymorphisms and susceptibility to melanoma." (PMID 30321335, 2019). "In summary, low calcemic vitamin D3 analogs such as 25(OH)D3, 21(OH)pD or calcipotriol showed similar antiproliferative activity to 1,25(OH)2D3 in melanoma cell lines expressing VDR spliced variants." (PMID 30200275, 2018). "WM98 and A375 melanoma cell lines express all four PCR fragments (Pr 1, Pr 2, Pr 4 and Pr 5) corresponding to VDR splicing variant c." (PMID 30200275, 2018). "Accordingly, VDR polymorphism and decreased levels of 25(OH)D3 in the serum positively correlate with melanoma prevalence and poor prognosis." (PMID 30200275, 2018). "In melanoma patients VDR polymorphisms have been largely studied for their role in the development of the disease, while their influence on prognosis and survival has been evaluated by a limited number of studies." (PMID 29100280, 2017). "The presence of VDR polymorphism was also investigated in a panel of melanoma cell lines used for experimental procedures." (PMID 28074906, 2017). "This meta-analysis identified that the VDR variants Bsm1 and Fok1 are significantly associated with melanoma risk, whereas four other variants—Apa1, Cdx2, EcoRV, and Taq1—are not." (PMID 25887475, 2015).
melanoma (continued). "We identified 10 suitable studies with a total of 4,961 melanoma patients and 4,605 controls which have described associations between common VDR variants and melanoma risk." (PMID 25887475, 2015). "We identified 10 eligible studies that evaluated six VDR variants (Apa1, Bsm1, Cdx2, EcoRV, Fok1, and Taq1) in a total of 4,961 melanoma patients and 4,605 controls." (PMID 25887475, 2015). "We identified eight eligible studies with a total of 4,189 cases and 4,084 controls that evaluated the association between the Fok1 VDR variant and melanoma risk." (PMID 25887475, 2015). "Five eligible studies with six subgroups encompassing 3,226 cases and 3,540 controls have previously examined the association between the Bsm1 VDR variant and melanoma risk." (PMID 25887475, 2015). "We have systematically reviewed the published epidemiological literature and conducted a meta-analysis to assess associations between common VDR variants and melanoma risk." (PMID 25887475, 2015). "Herein, we aim to clarify associations between VDR variants and melanoma risk via a meta-analysis of relevant published epidemiological studies." (PMID 25887475, 2015). "Hyperpigmentation of melanoma cells is also associated with a decrease of the VDR, RXR and PDIA3 mRNA levels in B16-F10 cells." (PMID 25811927, 2015). "Given the genetic and environmental interactions between VDR and UV light exposure during skin cancer development, many epidemiological studies have examined associations between VDR variants and melanoma risk." (PMID 25887475, 2015). "Six studies incorporating 3,858 cases and 3,110 controls investigated the association between the Taq1 VDR variant and melanoma risk." (PMID 25887475, 2015). "Seven studies examined a total of 3,621 cases and 2,783 controls to determine the association between the EcoRV VDR variant and melanoma risk." (PMID 25887475, 2015). "In particular, it has been reported that polymorphisms of VDR genes are associated with the occurrence of several cancers including melanoma." (PMID 26213971, 2015). "VDR variants have been found associated with the risk of developing melanoma; however, previous epidemiological studies are inconsistent." (PMID 25887475, 2015). "Although the data are by no means entirely consistent, a recent meta-analysis showed that polymorphisms at two sites in the vitamin D receptor were associated with either reduced (Bsm 1 A allele) or increased (Fok 1 T allele) risk of melanoma." (PMID 25343963, 2014). "Calcitriol has anti-proliferative properties and vitamin D receptor (VDR) polymorphisms are associated with alterations in melanoma susceptibility and progression." (PMID 25563456, 2014). "Given the potential for prognostic significance in melanoma as well as a role as a possible future therapeutic target, the relationship between VDR polymorphisms and melanoma should be further investigated." (PMID 25563456, 2014). "Certain VDR polymorphisms show prognostic significance for melanoma, squamous cell cancer of the head and neck, and non–small-cell lung cancer." (PMID 24011168, 2013). "Information on both serum 25-hydroxyvitamin D3 levels and VDR variants are required to understand the role of 25-hydroxyvitamin D3 in melanoma risk." (PMID 23413917, 2013). "If VDR SNPs are associated with melanoma risk therefore, elucidating the relationship between VDR variants and nevi is an important step towards understanding the involvement of VDR and, indirectly, of 25-hydroxyvitamin D3, in melanoma carcinogenesis." (PMID 23413917, 2013). "The first study evaluated the levels of 25-hydroxyvitamin D3 at time of melanoma diagnosis and the second one analyzed the association between VDR genetic variants and risk of having a high nevus number." (PMID 23413917, 2013). "When we analyzed the effect of VDR variant and melanoma susceptibility, we found that SNP rs7975218 was also associated with decreased risk of multiple primary melanomas." (PMID 23413917, 2013).
melanoma (continued). "In a second group of melanoma patients, including 150 with low and 113 with high nevus number, 11 VDR SNPs were analyzed for their association with nevus number." (PMID 23413917, 2013). "In our study, significant associations have been detected between nevus number, the most potent phenotypic risk factor of melanoma and 3 out of 11 VDR SNPs." (PMID 23413917, 2013). "Meta-analysis of all reports published by 2009 supported the association between VDR functional SNPs BsmI (rs1544410) and FokI (rs2228570) and melanoma risk." (PMID 23413917, 2013). "The potential role of functional VDR variants such as FokI and BsmI in melanoma risk has been assessed by meta-analysis studies." (PMID 23413917, 2013). "In the present study, we show a comprehensive analysis of VDR and GC association with CM using data from a wide case-control study (530 melanoma cases and 314 controls) in a Spanish population." (PMID 23544077, 2013). "More recently a large SNP study showed that common inherited variants at VDR influence melanoma risk, providing further evidence supporting a role for 25-hydroxyvitamin D3 in melanoma susceptibility." (PMID 23413917, 2013). "The association between 25-hydroxyvitamin D3 levels and/or inherited variation in VDR and melanoma risk has been studied in few populations, mostly from northern countries such as England, USA, Poland and Germany." (PMID 23413917, 2013). "The relationship between VDR SNP rs7975128 and, respectively, low nevus number and less multiple primary melanoma, suggests the involvement of VDR, and in turn of 25-hydroxyvitamin D3, in melanoma susceptibility." (PMID 23413917, 2013). "The first study evaluated the levels of Vitamin D at time of melanoma diagnosis and the second one analyzed the association between VDR genetic variants and risk of having a high nevus number, the strongest phenotypic risk factor for melanoma." (PMID 23413917, 2013). "The Tt and the tt genotypes of the VDR-Taq I-polymorphism showed an association with a decreased melanoma risk compared to the TT genotype, whereas the VDR-Fok I Ff genotype was associated with an increased risk to develop melanoma compared to the FF genotype." (PMID 22576141, 2012). "The decrease on the expression of VDR (vitamin Dreceptor) gene was linked to progression of pigmented skin lesions as well as shorter patients' melanoma overall survival." (PMID 22984562, 2012). "Vitamin D receptor (VDR) gene SNPs the FokI T allele was associated with increased melanoma risk (OR 1.42, 95% confidence interval CI 1.06-1.91)." (PMID 22759494, 2012). "In another study, the Taq I (rs731236) and the Fok I (rs2228570) SNPs of the VDR gene were analyzed for their melanoma risk association." (PMID 22576141, 2012). "The association of Taq 1 and Fok 1 restriction fragment length polymorphisms of the vitamin D receptor with occurrence and outcome of malignant melanoma (MM), as predicted by tumour (Breslow) thickness, has been reported previously." (PMID 15238985, 2004). "However, abnormalities in this pathway, such as reduced VDR expression, are closely linked to melanoma progression and poor prognosis." (PMID 40331942, 2025). "For example, VDR variants FokI, ApaI, and BsmI may influence the susceptibility to developing melanoma." (PMID 38927967, 2024). "Changes in vitamin D activation, local and systemic levels, and VDR signaling pathways can all lead to a loss of vitamin D anticancer protection, which may also promote the development of melanoma." (PMID 38672780, 2024). "The A allele of the VDR gene was shown to be substantially correlated with both metastasis and melanoma susceptibility in a study that examined the significance of VDR polymorphisms in melanoma risk." (PMID 38672780, 2024).